EGFR (epidermal growth factor receptor)
Diseases named in the same sentence as EGFR in open-access papers (continued):
Sharing a sentence is not in itself a finding about the gene and the disease.
tumor (continued). "It was shown that right‐sided tumours exhibit lower responsiveness to anti‐EGFR treatment and higher mutation rates in genes like BRAF, PIK3CA, and KRAS, suggesting potential underlying reasons for this association." (PMID 40302146, 2025). "Compared with non-Asian populations, Asian NSCLC patients exhibit a higher prevalence of EGFR mutations, distinct immune-related gene expression profiles, and specific gut microbiome compositions that can modulate the tumor immune microenvironment." (PMID 41347089, 2025). "Reprogramming of tumor cells towards kinases such as EGFR, CDK2, and CDK7 has been implicated in resistance to the CDK4/6i palbociclib in ER-positive breast cancer." (PMID 40949156, 2025). "In contrast, no significant grade-dependent differences were observed for EGFR or EpCAM in our cohort, although other studies have reported a positive association between EGFR expression and tumor grade." (PMID 40806559, 2025). "Patients with BM and those harboring EGFR amplification or high tumor mutation load gained significant more benefits in PFS from gefitinib + anlotinib." (PMID 39712454, 2025). "AT13387 has been observed to effectively reduce the expression of surface proteins, such as epidermal growth factor receptor, which are commonly associated with tumor aggressiveness and poor prognostic outcomes." (PMID 40276502, 2025). "To achieve this, we systematically analyzed 21 CRC tumor resection samples from 20 patients, encompassing both primary tumors (n = 12) and intrahepatic metastases (n = 9), with a focus on the EGFR‐associated interactome and downstream signaling pathways." (PMID 41319168, 2025). "Studies have found that the methylation status of some genes related to the EGFR signaling pathway changes in resistant cells, leading to sustained activation of the EGFR signaling pathway, causing tumor cells to develop resistance to TKI." (PMID 41394878, 2025). "FBXW7 mutations reduce EGF dependency, enhance MAPK/EGFR signaling, promote proliferation, and confer resistance to anti-EGFR therapies, thereby driving tumor progression." (PMID 41373479, 2025). "And, this new method can be used to detect the EGFR mutation in tumor samples including tissue and blood." (PMID 40587690, 2025). "This system incorporated two distinct lines of patient-derived tumor organoids (PDTOs) harboring EGFR mutations." (PMID 39747003, 2025). "We herein report a case of EGFR-mutated metastatic lung squamous cell carcinoma with a high tumor proportion score (TPS) of programmed death ligand 1 (PD-L1), where chemotherapy plus pembrolizumab therapy had a durable efficacy." (PMID 40351934, 2025). "All had biopsy-proven adenocarcinoma, 18 (94.6%) had tumours harbouring an EGFR mutation (exon 19 deletion, n = 6; exon 21 L858R, n = 10; exon 20 S768I, n = 1; exon 18 G719X, n = 1) and 1 (5.3%) harbouring an ELM4-ALK fusion." (PMID 41212380, 2025). "We previously developed a 2nd generation 4-1BB co-stimulated chimeric antigen receptor (CAR) targeting tumor-specific variant of the epidermal growth factor receptor (EGFRvIII) for treating patients with GBM." (PMID 40821779, 2025). "High EGFR expression, observed in over 70% of the tumor samples, was significantly associated with reduced overall survival, and multivariate analysis identified it as an independent risk factor." (PMID 40699851, 2025).
tumor (continued). "For example, tumor cells with mutations in the epidermal growth factor receptor (EGFR) are more dependent on cysteine, increasing their sensitivity to the inhibition of SLC7A11 and the depletion of GSH, which induces ferroptosis." (PMID 40709182, 2025). "ROC curve analysis was performed to obtain cutoff values of serum tumor marker concentrations that can predict EGFR mutation in serum liquid biopsy." (PMID 40510243, 2025). "The results of numerous foundational studies and clinical trials have consistently highlighted the significant association between EGFR signaling and tumor angiogenesis 12, 39-41." (PMID 39816681, 2025). "IGF1R protein expression is associated with tumour progression, while co-overexpression of EGFR and IGF1R has been independently confirmed in 64% (48/75) of ESCC patients." (PMID 40615716, 2025). "EGFR mutations were associated with smoking history (P=0.0311), tumor size (P=0.0247), tumor subtype (P=0.0003), rhabdomyoid differentiation (P=0.0237) and extracellular mucus (P=0.0013)." (PMID 40182027, 2025). "Particularly in NSCLC, aberrant EGFR signaling is closely associated with malignant biological behaviors, including invasion and metastasis, tumor angiogenesis and chemoresistance." (PMID 40523886, 2025). "During the preclinical development of TAVO412, the antitumor effects were evaluated in various tumor cell line-derived xenograft (CDX) models as well as in patient-derived tumor (PDX) models with different EGFR and c-Met expression levels and mutations." (PMID 39995668, 2025). "In the EP group, 12 tumours had pathogenic mutations in key genes associated with response to anti‐EGFR therapy (1 × in BRAF + PTEN, 1 × in BRAF + PIK3CA, 2 × in BRAF, 3 × in PTEN, 2 × in NRAS, 1 × in KRAS, 1 × in HRAS and 1 × in PIK3CA)." (PMID 40302146, 2025). "Overexpression of EGFR is associated with aggressive tumor behavior and poor prognosis in several cancers and CCA." (PMID 41425711, 2025). "Studies have indicated that the ratio of CD8+ tumor infiltration lymphocytes (TILs) was associated with immunotherapy efficacy; however, it was significantly lower in EGFR-mutant than wild type patients." (PMID 40002895, 2025). "In contrast, overexpression is associated with tumour development across a wide range of cancers, an effect that EGFR-specific monoclonal antibody inhibitors can prevent." (PMID 39919333, 2025). "Including molecular biomarkers beyond MGMT, like IDH1/2 mutation status, ATRX loss, TERT promoter mutation, EGFR amplification, and 1p/19q co-deletion, can improve the model’s understanding of tumor biology." (PMID 41584616, 2025). "Research into additional predictive biomarkers for EGFR inhibition, beyond mutation status and tumor sidedness, is ongoing." (PMID 40982295, 2025). "Based on the internal and external validation results, we validated the clinical use of EAGLE for the prediction of EGFR mutations in LUAD samples extracted from the primary tumor site by running a silent trial at MSKCC." (PMID 40634781, 2025). "First, single-modality imaging data primarily reflect tumor morphology or functional characteristics, failing to capture molecular dynamics or microenvironmental heterogeneity linked to EGFR mutations." (PMID 40708937, 2025). "EGFR, a receptor tyrosine kinase that is mutated in many tumor cell types, plays a key role in tumor cell proliferation and tumor vascularization." (PMID 40723181, 2025). "While some heterogeneity can arise from having multiple mutations in the tumor, EGFR driver mutations are considered as an early event in tumor evolution, and mutational mosaicism is rarely detected in patient tissues." (PMID 39747003, 2025). "Their occurrence is nonetheless reduced in osimertinib, owing to its enhanced activity against tumor EGFR carrying the mutations del19, L858R, and T790M, compared to wild-type EGFR." (PMID 40422529, 2025).
tumor (continued). "Lapatinib targets both EGFR and HER2, reducing tumor cell proliferation and survival, particularly in GC with EGFR/HER2 overexpression or mutation." (PMID 40281132, 2025). "Understanding the molecular interplay between EGFR mutations and tumor behavior is essential for advancing therapeutic interventions and optimizing patient outcomes." (PMID 40628732, 2025). "Molecular profiling was performed to clarify the tumor origin and guide therapy further, revealing an EGFR exon 21 L858R mutation." (PMID 40740944, 2025). "Aberrant EGFR activation has been strongly associated with tumor progression and therapeutic resistance, underscoring its importance as a molecular target for anticancer interventions." (PMID 41449180, 2025). "Specific EGFR mutations, including exon 19 deletion, L858R, and T790M, significantly enhance tumor sensitivity to EGFR tyrosine kinase inhibitors (EGFR-TKIs)." (PMID 41439947, 2025). "In contrast, other baseline characteristics—including age, gender, BMI, histological subtype, tumor marker levels, and clinical stage—had limited effects on the AUC of EGFR mutation prediction." (PMID 41415549, 2025). "Researchers have investigated the heterogeneity of EGFR mutation-positive NSCLC tumor cells through the lens of clonal evolution, proposing that EGFR-TKI resistance is intricately linked to a high degree of intracellular heterogeneity." (PMID 40003951, 2025). "In our study, from a consecutive series of 100 EGFR mutated ADCs, only 32 underwent tumor rebiopsy at progression time and 4 (12%) showed histological transformation." (PMID 41226501, 2025). "Small molecule inhibitors targeting EGFR can be effective in slowing the progression of disease, and in some settings these drugs even cause dramatic tumor regression." (PMID 40291701, 2025). "The other five high‐order texture features associated with tumor heterogeneity, which are associated with EGFR mutation status in NSCLC patients, cannot be detected by the naked eye." (PMID 39673508, 2025). "An important consideration is how spatial and temporal heterogeneity in EGFR-mutated NSCLC is a prime example of how diversity within the tumor and its evolution under drug selective pressure can be the main cause of resistance and relapse." (PMID 40647400, 2025). "The presence of HER3 is particularly notable in left-sided CRC, where it is linked to aggressive tumour features, resistance to anti-EGFR therapies, and poor prognosis." (PMID 40940907, 2025). "These mutations make the tumor sensitive to drugs called EGFR tyrosine kinase inhibitors (EGFR-TKIs)." (PMID 40647400, 2025). "Potentially due to the smoking history, KRAS-mutant tumors typically manifest a higher tumor mutational burden (TMB) than their EGFR-mutant counterparts." (PMID 40524071, 2025). "Abnormal EGFR activation or mutation can lead to sustained activation of these signaling pathways, promoting tumor development and progression." (PMID 40347011, 2025). "Oncogenic activation of MAPK signaling, particularly via RAS and BRAF mutations, is known to promote aggressive tumor behavior and confer resistance to EGFR-targeted therapies in CRC patients." (PMID 40227607, 2025). "Based on this theory, primary BRAF/EGFR co-mutated patients have a higher propensity to develop dominant BRAF-mutated tumor clones following resistance to EGFR TKIs treatment." (PMID 40242250, 2025). "Second, the absence of heavy mutagenic exposure yields a comparatively low tumour-mutational burden, reinforcing ‘oncogene addiction’ to mutant EGFR and prolonging sensitivity to potent third-generation inhibitors." (PMID 40894225, 2025). "This raises uncertainty regarding the reliability of tumor diameter as a predictor of EGFR mutation status." (PMID 41244899, 2025).
tumor (continued). "In summary, tumor-associated macrophages, immune responses, and fibroblasts within the tumor microenvironment play pivotal roles in the development of EGFR-TKI resistance." (PMID 40003951, 2025). "This study used a computer‐based methodology with two Convolutional Neural Networks (CNNs) based on InceptionResNet‐V2, applied to Whole Slide Images, to distinguish healthy from cancerous tissue and then EGFR mutated tumor tissue samples." (PMID 40965349, 2025). "In GB, genetic alterations such as amplification, mutation, and overexpression of the EGFR gene lead to hyperactivation of the signaling pathway, promoting tumor growth and progression." (PMID 39940838, 2025). "Understanding the mechanisms underlying tumor heterogeneity is essential for overcoming resistance to EGFR-TKI therapy." (PMID 40003951, 2025). "EGFR dysregulation, especially via amplification or constitutively active variants like EGFRvIII, enhances tumor proliferation, invasiveness, and resistance to standard therapies, including radiotherapy and TMZ." (PMID 41346390, 2025). "These MOAs manifested in in vivo antitumor activities of TAVO412 in a diverse panel of NSCLC tumor models with varying EGFR mutations, a broad range of EGFR and cMET receptor densities, and VEGF secretion levels." (PMID 40452841, 2025). "It not only deepens our understanding of the tumor microenvironment and cellular heterogeneity associated with EGFR-TKI resistance but also identifies potential biomarkers of resistance." (PMID 40003951, 2025). "Compared with normoxic conditions, hypoxic conditions caused EGFR phosphorylation in all of these tumor cell lines to various extents, suggesting that hypoxia is sufficient to induce EGFR phosphorylation in the absence of EGFR ligands." (PMID 40940319, 2025). "In this case, the development of HPD was associated with a high postoperative tumor burden, elevated PD-1 expression, and aberrant activation of signaling pathways mediated by EGFR, MET, and FGFR1 amplifications." (PMID 40575167, 2025). "The difference between EGFR and EGFRvIII is that the latter is a constitutively active mutant variant causing uncontrolled growth behavior in the tumor." (PMID 39936963, 2025). "This phenomenon is closely linked to heightened EGFR activity in tumor cells; specifically, activated EGFR signaling can enhance COX-2 transcription and upregulate the production of prostaglandin E2, further amplifying EGFR activity." (PMID 40141751, 2025). "Tumors harboring EGFR variants can evade immune response by exposing PD-L1 on tumor cells and inhibiting T-cell antitumor activity." (PMID 40809430, 2025). "Focal/regional progression (with overall disease control at other sites) can occur due to tumor heterogeneity, with the selective pressure of EGFR-TKIs causing the outgrowth of subclones with pre-existing or acquired alterations conveying a fitness advantage." (PMID 40647500, 2025). "Previous studies showed that EGFR mutation preferentially occurred in patients with maximal tumor size less than 3 cm." (PMID 40182027, 2025). "Of clinical interest, elevated levels of activated IGF1R have been detected in tumor samples obtained from patients with EGFR-mutated NSCLC who developed resistance to osimertinib." (PMID 40243603, 2025). "Another FAK inhibitor based on the same scaffold is TAE226, which has an IC50 of 5.5 nM and can exert significant anti-tumour activity in non-small cell lung cancer carrying EGFR mutations, including the T790M mutation." (PMID 40045379, 2025). "In mice with TKI-resistant lung tumors, WQQ-345 not only slowed tumor growth but actually caused regressions in combination with EGFR blockade—effectively re-sensitizing the tumors to the treatment they had previously evaded." (PMID 41502503, 2025).
tumor (continued). "We integrated several parameters from a tumor‐intrinsic and tumor‐extrinsic perspective to explain how EGFR activation and mutation affect the effectiveness of immunotherapy." (PMID 40859900, 2025). "The RT-qPCR-based assay identified EGFR variants with high accuracy (overall concordance rate 94.3%) over a broad range of clinical sample types, variant allele frequencies, tumor cell contents and deoxyribonucleic acid (DNA) input amounts." (PMID 40299437, 2025). "Of 28 patients with circulating tumor DNA (ctDNA) testing, 22 (78.6%) showed clearance of EGFR mutation after 2 or 4 cycles." (PMID 40088185, 2025). "Co-mutated tumours were dominated by EGFR-L858R (71%) and frequently harboured high-level MET amplification (57%)." (PMID 41316444, 2025). "Despite the T790M mutation, the activation of the EGFR pathway remains the primary driver of tumor progression." (PMID 39741120, 2025). "Future prospective cohort studies with complete clinical annotation are warranted to further elucidate the interaction between tumor stage or combination chemotherapy regimens and anti-EGFR monoclonal antibody-associated adverse events." (PMID 41049433, 2025). "EGFR alterations, including amplification and the EGFRvIII mutation, are associated with aggressive tumor biology and resistance to therapy." (PMID 40722305, 2025). "Given the high concordance (approximately 80%) of genomic mutation profiles between CTCs and tumor biopsies, using CTCs as a surrogate target to investigate EGFR mutation profiles shows promise for patients with NSCLC." (PMID 41439947, 2025). "The microenvironment for EGFR-mutated tumors is immunosuppressive, and EGFR-TKIs can regulate tumor immune microenvironment by affecting the expression of tumor cell antigens and infiltration of immune cells." (PMID 40831747, 2025). "In conclusion, our study demonstrates that IL-35, secreted by immunosuppressive cells recruited in response to EGFR mutations, contributes to suppressing NK cell function and promoting tumor progression in NSCLC." (PMID 41357575, 2025). "Feature extraction from PET/CT images can not only effectively predict EGFR mutations but also provide auxiliary decision support for tumor staging, efficacy evaluation, and targeted therapy." (PMID 41002349, 2025). "EGFR overexpression was associated with a poor prognosis in patients with intracranial grade II tumours (p = 0.002)." (PMID 40227788, 2025). "NK cells play a critical role in tumor suppression but are often phenotypically inactive in EGFR-mutated NSCLC due to high levels of TGF-β in the TME." (PMID 40733125, 2025). "In summary, our research revealed that the EGFR mutation state was associated with smoking history, histological subtypes, tumor size, and some rare histological features, such as rhabdomyoid differentiation and extracellular mucus." (PMID 40182027, 2025). "Overall, our study supports the notion that morphological patterns can guide minimal tumour sampling coverage to identify relevant mutations relevant for prediction of response to anti‐EGFR therapy." (PMID 40302146, 2025). "Comparable mutations have also been identified in EGFR-mutant tumor specimens exhibiting acquired resistance to erlotinib, another EGFR inhibitor." (PMID 40342734, 2025). "By suppressing EGFR-dependent pathways, these antibodies slow tumour growth and enhance cancer cell susceptibility to treatments like chemotherapy and radiation therapy." (PMID 40265416, 2025). "Multivariate analysis further confirmed tumor surface area as an independent predictive factor for EGFR mutations." (PMID 41244899, 2025). "Beyond promoting tumor growth, EGFR mutations significantly alter cancer metabolism, increasing glucose uptake, lactate production, and the pentose phosphate pathway." (PMID 41142757, 2025). "Altogether, the association between EGFR.Sig and tumor immunosuppression suggests its potential to serve as a predictive biomarker of immunotherapy." (PMID 40574864, 2025).